JUN (Jun proto-oncogene, AP-1 transcription factor subunit)
Diseases named in the same sentence as JUN in open-access papers (continued):
Sharing a sentence is not in itself a finding about the gene and the disease.
synovitis (1 paper, 2023). Inflammation of a synovial membrane. "Third, the underlying regulatory and downstream mechanisms of JUN and ZFP36 in synovitis require further studies." (PMID 37741987, 2023). "The lower transcript levels of JUN and ZFP36 were predicted and validated in OA-associated synovitis, and this approach has high diagnostic efficacy for OA-associated synovitis." (PMID 37741987, 2023). "In the present study, we observed an inconsistency between the expression and transcription of JUN in synovitis." (PMID 37741987, 2023). "Two genes, i.e., JUN and ZFP36, were identified by screening the DEGs associated with synovitis." (PMID 37741987, 2023). "The ROC curve analysis suggested that JUN and ZFP36 expression has a predictive value in the development of synovitis during the OA process, with the maximum AUC value reaching 0.78 and 0.74, respectively." (PMID 37741987, 2023). "Moreover, the low transcription level of the JUN gene can be considered a negative feedback regulation triggered by iron overload in synovitis." (PMID 37741987, 2023).
Tinnitus (1 paper, 2022). Tinnitus is an auditory perception that can be described as the experience of sound, in the ear or in the head, in the absence of external acoustic stimulation. "The core components of Liuwei Dihuang Pill in the treatment of tinnitus including quercetin, stigmasterol, kaempferol, β-sitosterol, tetrahydroalstonine, which may act on core targets such as STAT3, transcription factor AP-1 (JUN), tumor necrosis factor (TNF), interleukin-6 and MAPK3." (PMID 36401375, 2022).
uremia (1 paper, 2023). A clinical syndrome associated with the retention of renal waste products or uremic toxins in the blood. "Indeed, targeted deletion analysis in our study indicates that AP-1 and the constitutive element c-FOS rather than c-JUN bind to the KLF2 promoter sequence -464 to -441 to regulate the inhibition of KLF2 in uremia." (PMID 37795100, 2023).
uveitis (1 paper, 2023). An inflammatory process affecting a part of or the entire uvea. "In addition, studies have shown that MAPK1, RELA, and JUN can effectively control the progression of uveitis." (PMID 37653797, 2023). "JUN, RELA, and MAPK may play important roles in the treatment of uveitis by SNS." (PMID 37653797, 2023).
viral pneumonia (1 paper, 2026). Inflammation of the lung parenchyma that is caused by a viral infection. "Through the construction of a comprehensive PPI network, we identified six core targets, including STAT3, AKT1, PIK3CA, PIK3R1, JUN, and MAPK1, which are likely central to the mechanism of action of DLQGD in viral pneumonia." (PMID 41601832, 2026).
tumor (866 papers, 1998 to 2026). "Our data show that c-JUN signaling is repressed in p63 + /Ki67+ tumor stem-like cells and rather activated after the loss of the proliferation marker Ki67, indicating a function in differentiation." (PMID 39358322, 2024). "As a result, JUN depletion in Pten-deficient prostates interfered with the senescence-associated immune clearance and accelerated tumor growth." (PMID 38811984, 2024). "JUN can cause the migration and infiltration of tumor cells, consistent with the function of CAP2 in GC cells." (PMID 37707957, 2023). "In line with transcription regulatory effects in cell models, IHC analysis of tumor samples showed a significant reduction of VEGFC protein levels in JUN-deficient stroma." (PMID 36438487, 2022). "ZFP36 is downregulated in the tumor compared with normal samples, and co‐expressed with JUN, JUNB, FOS, and FOSB, downregulation of which was associated with poor outcomes and BC progression." (PMID 35037412, 2022). "We examined the association between JUN mRNA levels and organ-specific metastasis within 82 tumor samples based on a published dataset (GSE2603)." (PMID 29667003, 2019). "We showed herein that there possibly exists a new mechanism in which a DLBCL associated circulating miRNA signature suppresses JUN signaling before tumor formation while promoting MYC oncogenic factors." (PMID 28107482, 2017). "But compared with non-tumor tissues, a loss of JUN was observed in 38% HCC tumors and expression of JUN was significantly lower in 70% HCC tissues, and these data are consistent with our results." (PMID 27454179, 2016). "One defined “hallmark” of tumor formation is a deregulated cell cycle and c-JUN's ability to effect this represents a further way in which the protein contributes to tumorigenesis." (PMID 21789792, 2011). "The JUN gene encoded the c-Jun protein, a significant TF belonging to the AP-1 family that was essential to the development of cancer, particularly in controlling the proliferation and death of tumor cells." (PMID 40406148, 2025). "A recent study provides novel insights how the tumor-suppressive functions of AP-1 might be exerted, as JUN was particularly implicated as pioneering factor in bookmarking the enhancers of genes associated with the induction of the senescence program." (PMID 38811984, 2024). "APC-mutated mice had reduced tumor size and number upon inactivating JUN." (PMID 36457029, 2022). "Moreover, the PBRM1‐deficient cell lines were shown more sensitive to irradiation, and targeted inhibition of c‐JUN can prevent tumour progression caused by PBRM1 deficiency." (PMID 36178086, 2022). "It is also possible that other FOX, HOX, GATA, and JUN/AP‐1 family members could be associated with tumor/normal ARBSs and could influence differential AR binding." (PMID 31520575, 2019). "Using mouse models, c-JUN has been implicated in tumor formation in both skin and liver." (PMID 21789792, 2011). "Interestingly, the authors reported that the proto-oncogene JUN (which encodes the transcription factor c-Jun and is a central hub in the protein–protein interactions of tumours that recur rapidly after platinum-based treatment) was exclusively upregulated in these AI-detected areas." (PMID 40282519, 2025). "Therefore, therapeutic activation of STAT3 potentially causes SASP factor modulation and may elevate JUN levels in tumors, thereby restricting tumor progression and enhancing PCa patient survival." (PMID 38811984, 2024). "In humans, this gene encodes a protein that can dimerize with JUN proteins to form transcriptional complex AP-1, which has been implicated as a oncogenic or anti-oncogenic regulator in cell proliferation, differentiation, apoptosis, and tumor invasion in various cancer types." (PMID 39273313, 2024). "Thus, JUN phosphorylation are associated with activated stroma and tumor invasiveness." (PMID 36438487, 2022).
tumor (continued). "Therefore, JUN deficiency in stroma indeed inhibits tumor progression and metastasis in vivo." (PMID 36438487, 2022). "To probe mechanisms underlying DKK3's tumor‐suppressive role in acinar cells, we performed pre‐ranked GSEA on the DD versus WT RNA‐seq data, which highlighted MAPK, JUN, and DMP1 pathways, with Fos emerging as a key regulator." (PMID 41147409, 2026). "In WT tumor cells, regulons associated with NFKB1, XBP1, JUN, SREBF2, and EHF exhibited elevated activity." (PMID 40767963, 2025). "Cell subtypes in an activated state, which directly kill tumour cells, like CD8_Tact_JUN (C34), NK_FCGR3A (C41) and CD8_Teff_GZMK (C36), were more prevalent in GC samples." (PMID 40785647, 2025). "Relevant studies have suggested that activation of the JNK/c-JUN pathway in response to IR stimulation promotes tumor cell apoptosis." (PMID 40410897, 2025). "SPIC and MAFB were predominantly expressed in normal and adjacent tissues, while SPP1+ TAM-associated TFs (SREBF1, JUN, SPI1, and CREB1) showed peak expression in tumor core regions." (PMID 40725473, 2025). "Patients with low MAP2K4, MAP2K7 or MAPK8 expression or high MAPK9 or JUN in their tumours had greater metastatic frequency following tamoxifen treatment." (PMID 40826108, 2025). "The overexpression of GPX3 and JUN demonstrates significant tumor-suppressive activity, highlighting their potential as effective therapeutic targets in combating TC." (PMID 40092686, 2025). "Subcutaneous tumor specimens were subjected to immunohistochemical (IHC) staining for Ki67, p-c-JUN, and RUNX2 proteins, along with TdT-mediated dUTP nick-end labeling (TUNEL) staining for apoptosis detection." (PMID 40410897, 2025). "Our study identified and validated the roles of GPX3 and JUN as tumor suppressors in the progression and metastasis of TC through various analytical methods." (PMID 40092686, 2025). "JUN is a basic leucine zipper (bZIP) protein, a cancer protein that regulates human tumor transformation and development, and is expressed in both immune and inflammatory cells." (PMID 41439108, 2025). "Differential gene expression highlighted immune regulation pathways and transcriptional networks centered on JUN, JUNB, and FOSB, linked to immune suppression and tumor progression." (PMID 42004296, 2025). "TTN mutations also inhibit ANKRD1 expression via JUN disruption and enhance CD4/CD8 T‐cell infiltration, improving anti‐tumour immunity and outcomes." (PMID 39748197, 2025). "In tumor samples, JUN exhibited significantly lower expression in MSC1 and MSC2 (P < 0.05), while NFKB1 was significantly reduced in MSC2 and MSC3 (P < 0.01)." (PMID 40666524, 2025). "Module1 (Stress response) was characterized by expression of genes such as FOS and JUN,thus representing a stress-response-related signature in tumor cells." (PMID 40406120, 2025). "Genomic profiling revealed EGFR and JUN amplifications with NCOR1 and PRKAR1A losses, alterations linked to aggressive tumor biology." (PMID 40979503, 2025). "Further, we observed that targeting SIX4 attenuated the transformation of inflammation to cancer in intestinal epithelium via inactivating IL-6/STAT3/SIX4/c-JUN feedback loop, which subsequently suppressed DeltaNp63-mediated tumor stemness signals." (PMID 39309424, 2024). "Our findings provide evidence that loss of JUN accompanied by reduced activation of STAT3 bypasses SASP and subsequently amplifies the tumor load in JunPEΔ/Δ; PtenPEΔ/Δ animals." (PMID 38811984, 2024). "MORC3 deficiency downregulated the E-cadherin (CDH1) tumor suppressive gene and the keratin 14 (KRT14) epithelial differential marker but significantly upregulated the expression of oncogenic JUN, CCND1, CCND2, and CCN1 at the transcriptional level." (PMID 39329063, 2024).
tumor (continued). "Analysis of the transcriptomic data revealed that LGALS3 (an important regulator of the tumour microenvironment 28-30), which is a target gene of the transcription factor JUN, was the most significantly decreased gene following HDAC7 knockdown." (PMID 39629136, 2024). "The results of our murine PCa model reinforce our observations from human PCa samples, suggesting that JUN acts as a tumor-suppressor in PCa." (PMID 38811984, 2024). "JUN is stabilized upon S243 dephosphorylation mediated by calcineurin, promoting cell proliferation and tumor formation." (PMID 38926604, 2024). "To elucidate the tumor cell-specific molecular programs regulated by JUN in vivo, we performed transcriptome profiling of PE cells across all four experimental murine groups." (PMID 38811984, 2024). "As a crucial part of the CRC-related JNK signaling pathway, JUN can be regulated by numerous upstream targets to further impact tumor growth, CRC cell invasion, and apoptosis." (PMID 38675391, 2024). "The authors suggested a role for JUN (Jun proto-oncogene, AP-1 transcription factor subunit) in regulating the expression of iCCA-related genes and apoptosis of tumor cells." (PMID 39199659, 2024). "Accordingly, immunostaining in 41 tumor and unaffected adjacent tissues showed reduced levels of JUN; downregulation at the transcript level was also observed for JUN, FOS (Fos proto-oncogene, AP-1 transcription factor subunit), and CCND2." (PMID 39199659, 2024). "We observed a gradual decrease of JUN protein abundance from healthy tissue to primary tumors (low Gleason; Gleason score 5–6), reaching the lowest JUN expression state in advanced tumor stages (high Gleason; Gleason score 7–9)." (PMID 38811984, 2024). "FOS and JUN are B-cell receptor pathway modules and have been shown to be upregulated in tumor-infiltrating B cells in other solid tumors." (PMID 38110959, 2023). "There have been some inhibitors identified to date that target JUN, such as T-5224 and E3330, that exhibit distinct anti-tumor properties." (PMID 37375197, 2023). "Among the responders, we observed the activation of the PAX5 network in the immune regions adjacent (spatial gene expression clusters in direct contact) to tumor clusters, while FOS and JUN modules are highly active in CAFs surrounding the tumor spots." (PMID 37723590, 2023). "FOS and JUN are part of the upregulated module in premalignant samples and downregulated modules in tumour samples." (PMID 38157373, 2023). "HCC-CAF interactions were also enriched in the responding tumors and were associated with extracellular matrix (ECM) remodeling as there was high activation of FOS and JUN in CAFs adjacent to the tumor." (PMID 37723590, 2023). "The JUN protein is believed to play a significant role in tumor development and occurrence, mainly regulating tumor cell survival and apoptosis." (PMID 37375197, 2023). "It was proven by upregulated activation of the regulon or mRNA expression of JUN of CXCL12+ iCAF in the tumor tissues of patients with advanced-stage CRC." (PMID 37360193, 2023). "Downregulation of JUN with a concomitant G1-phase arrest is consistent with the function of c-Jun in promoting G0 to G1 transition and indicates the antiproliferative effect of sunitinib in tumor organoids of both RB subtypes." (PMID 36726110, 2023). "c-JUN and c-FOS, both well-established oncogenes, are considered to play a critical role in tumorigenesis, proliferation and transformation, angiogenesis, tumour invasion and metastasis, and their expression is associated with poor clinical outcomes." (PMID 36830725, 2023). "The specific FOS/JUN protein composition of AP-1 was found to regulate the ability of AP-1 to promote or inhibit tumor growth." (PMID 36980293, 2023).
tumor (continued). "Future work will be required to investigate the relationship between MTF-1 and FOS/JUN in tumor progression." (PMID 36980293, 2023). "Our above studies have shown that c‐JUN activation was involved in the tumour‐promoting effect of PBRM1 in HUTU‐80 cells." (PMID 36178086, 2022). "As examined by luciferase activity and histological analysis of liver tissues, the tumor dissemination was significantly obliterated by stromal JUN deletion." (PMID 36438487, 2022). "At the same time, the patients with positive expression of c‐JUN had larger tumour sizes, deeper invasion depths and more aggressive nerve invasion and vascular invasion than the negative patients (p < .05)." (PMID 36178086, 2022). "Studies have also shown that the expression levels of the N‐terminal kinases JNK and p‐c‐JUN of c‐JUN are significantly reduced when anti‐tumor drugs are used, which means that JUN plays a role in regulating cell‐cycle escape." (PMID 36176734, 2022). "The overexpression of CACNA2D1, JUN, GNG4, NGF, MYC, and MAPK4K4, components of the MAPK pathway, is associated with tumor aggressiveness and chemotherapy resistance." (PMID 36344487, 2022). "JUN is an oncogenic transcription factor that promotes tumor formation, chemoresistance, invasion, proliferation, migration, and metastasis, and serves as a marker for evaluating chemotherapeutic responses." (PMID 36118098, 2022). "MP1 was characterized by expression of genes such as FOS and JUN, thus representing a stress-response-related signature in tumor cells." (PMID 36423636, 2022). "CTNNB1 binds directly various transcription factors, which are important for tumor progression including JUN, FOSL1, SRY box transcription factor 17 (SOX17), TCF3, TCF4, and TCF7." (PMID 36457029, 2022). "The oncogenic transcription factors FOS and JUN, highly expressed in post-treatment tumors, were also upregulated in the stroma (tumor stroma and remission stroma) around post-treatment tumors." (PMID 36505794, 2022). "In line with the transcriptomic data, JUN was also expressed by SOX10- cells such as ganglionic-like tumor cells in GNs and tumor cells in NBs." (PMID 33712610, 2021). "AGTR2 was positively related with JUN, a common transcription factor promoting tumor proliferation in both adrenocortical carcinoma (ACC; Cor = 0.614) and TGCT (Cor = 0.589)." (PMID 34671200, 2021). "We provided in vitro and in vivo evidence that the four miRNA of the prognostic model modulated Ras protein signal transduction via IGF1 and JUN, indicating an alternative mechanism for oncogenic signaling and tumor progression in DLBCL." (PMID 33107145, 2021). "Another AP-1 family member, JUN, was the first oncogene to be described and has since been studied in detail in the context of various tumor entities." (PMID 34544361, 2021). "We noticed that several TF-regulating genes, including FOS and JUN, appeared to be particularly important during tumour evolution." (PMID 33441952, 2021). "Immunohistochemistry was performed to show the protein levels of IGF1 and JUN in tumor samples of 52 DLBCL patients." (PMID 33107145, 2021). "JUN presented low-expression in both normal and tumor tissues, whereas ANO6 presented high-expression." (PMID 34715817, 2021). "Along with the TFs NF‐κB, C/EBPβ, ETS2, and HIF1A that have been well‐documented as tumor promoters, JUN and its 17 downstream target genes were also categorized in this highly active module." (PMID 34459128, 2021). "PDCD4, a well-known tumor suppressor upregulated in our study, has been suggested to interact with c-JUN, blocking c-JUN phosphorylation by JNK." (PMID 32260415, 2020).